PTTG3P (pituitary tumor-transforming 3, pseudogene)
Diseases named in the same sentence as PTTG3P in open-access papers (continued):
Sharing a sentence is not in itself a finding about the gene and the disease.
squamous cell carcinoma (1 paper, 2020). A carcinoma arising from squamous epithelial cells. "In the group of squamous cell carcinomas, the highest fold change of PTTG3P was observed for LUSC (7.26), while the lowest for CESC (1.36); For HNSCC, a 1.39-fold change was indicated." (PMID 32824814, 2020). "Firstly, the expression levels of PTTG3P and two other members of the PTTG family, PTTG1 and PTTG2, were analyzed across twenty-four different cancers, including squamous cell carcinomas, adenocarcinomas and other cancers based on data from the UALCAN database." (PMID 32824814, 2020).
tumor (27 papers, 2017 to 2025). "Clinically, high PTTG3P expression significantly associates with tumor size and TNM stage and shorter survival time." (PMID 34660259, 2021). "Clinically, high PTTG3P expression considerably associates with tumor size and TNM stage as well as shorter survival time." (PMID 34132347, 2021). "The association between tumor size and PTTG3P expression was also confirmed by analysis of samples in cohort 1(P = 0.041)." (PMID 29803224, 2018). "The enhanced tumour cell proliferation and invasiveness caused by abnormally high expression of PTTG3P thus resulted in more aggressive biological behaviour, leading to shortened DFS and OS in patients with GC." (PMID 28631396, 2017). "Moreover, PTTG3P has been demonstrated to promote tumor cell proliferation and invasion in gastric and liver cancers In order to explore the biofunction of PTTG3P in PDAC cells, we performed gain of- and loss of function experiments in PDAC cell lines." (PMID 33298873, 2020). "Elevated PTTG3P was associated with larger tumor size and poorer differentiation." (PMID 33298873, 2020). "Simultaneous silencing of the PTTG1, PTTG2, and PTTG3P genes was performed in same MG-63 cells using siRNA to investigate their combined effects on key cellular processes such as cell cycle regulation, tumor growth, and other critical cellular functions." (PMID 39139816, 2024). "We also have conducted xenograft tumor models and an experimental blood-lung metastasis model using A549 cells overexpressing PTTG3P." (PMID 37705754, 2023). "We found the pseudogene-derived lncRNA PTTG3P is upregulated in NSCLC and associated with larger tumor size, advanced staging, and poor prognosis." (PMID 37705754, 2023). "These in vivo data provide stronger support for our conclusions that lncRNA PTTG3P acts as an oncogene by promoting tumor growth and metastasis in NSCLC." (PMID 37705754, 2023). "They showed that PTTG3P upregulation was positively associated with TNM stage, tumor size, and poor survival of patients." (PMID 36770654, 2023). "Nude mice model was used to examine the effects of PTTG3P on tumor cell growth and metastasis in vivo." (PMID 37705754, 2023). "To further demonstrate the oncogenic role of PTTG3P in promoting tumorigenesis and metastasis, we have conducted xenograft tumor models and an experimental blood-lung metastasis model using A549 cells overexpressing PTTG3P." (PMID 37705754, 2023). "H&E staining showed that the xenograft tumors displayed typical characteristics of tumor cells, while the Ki-67- and Bcl-2-positive cells in the PTTG3P knockdown group were significantly lower than those in the control group." (PMID 37705754, 2023). "The results showed that the tumor size and weight at 15-21 days in the PTTG3P knockdown group were significantly lower than those in the control group." (PMID 37705754, 2023). "Meanwhile, elevated FOXM1 transcriptionally activated PTTG3P, thereby forming a feedback circuit to enhance the tumor-promoting effect induced by PTTG3P." (PMID 35651786, 2022). "This study also showed that the overexpression of lncRNA PTTG3P induces tumor growth and metastasis in vitro and in vivo, through the modulation of PTTG1/PI3K/AKT signaling." (PMID 36010685, 2022). "Under the action of hypoxia-inducible factor-1-α (HIF-1α), the hypoxia environment induces the overexpression of PTTG3P to promotes M2 polarization and stimulates tumor development." (PMID 35145526, 2022). "Related studies found that lncRNAs HLA-F-AS1, NBR2, PTTG3P, and RPPH1 induce the polarization response of tumor-associated Mφs by acting on the corresponding targets or pathways, thus participating in the pathological development of CRC." (PMID 35145526, 2022). "The expression of LncRNA PTTG3P was significantly enhanced in CRC tumor tissues and thus became the focus of the present study." (PMID 34660259, 2021).
tumor (continued). "In this study, higher PTTG3P expression was found in the kidney renal clear cell carcinoma tissues, and PTTG3P expression was significantly correlated with individual cancer stage and tumor grade of the patients." (PMID 33845847, 2021). "For instance, pseudogene pituitary tumor-transforming 3 (PTTG3P) is upregulated in PDAC tissue and is associated with larger tumor size and reduced overall survival." (PMID 34820419, 2021). "PTTG3P induced tumor growth and invasion through miR-132-3p sponging that resulted in FOXM1 targeting." (PMID 34419060, 2021). "Through gain and loss of function approaches, the role of lncRNA PTTG3P was validated in relevant CRC cells and subcutaneous tumor model." (PMID 34660259, 2021). "It has been observed that there were correlations between the PTTG3P up regulation, larger tumor size, poor prognosis, and poor differentiation in PDAC tissues." (PMID 34419060, 2021). "In this study, we demonstrated that a pseudogene, PTTG3P, was positively correlated with tumor aggressiveness and promoted cancer progression via a PTTG3P/miR-132/212-3p/FoxM1 feedback loop." (PMID 33298873, 2020). "Functional study revealed PTTG3P promote tumor growth and metastasis via functioning as a ceRNA for miR-132/212-3p, thereby preventing its association with target FoxM1 mRNA." (PMID 33298873, 2020). "Clinical data revealed that elevated PTTG3P closely correlated with larger tumor size, poorer differentiation and reduced overall survival." (PMID 33298873, 2020). "Results from transwell and scratch wound assays confirmed similar role of FoxM1 on PTTG3P-induced pro-tumor biofunctions." (PMID 33298873, 2020). "Treatment of 5-fluorouracil decreased PTTG3P expression in tumor cells, and enhanced-expression of PTTG3P partially attenuated 5-fluorouracil-induced cell apoptosis." (PMID 33298873, 2020). "Given that PTTG3P enhances cell proliferation and migration/invasion in vitro, we further assessed the tumorigenic ability of PTTG3P in tumor growth and cancer cell dissemination using xenograft mouse models." (PMID 33298873, 2020). "Elevated PTTG3P expression correlated with larger tumor size and worse differentiation, and reduced overall survival." (PMID 33298873, 2020). "Considering that metastasis is an important factor involved in tumor progression, we aimed to investigate the effect of PTTG3P on cell migration and invasion." (PMID 31340767, 2019). "Firstly, we analyzed the profiles of HCC patients from the Gene Expression Omnibus (GEO) (GSE 76427 and GSE 84402 dataset), and found that PTTG3P was up-regulated in HCC tissues compared to adjacent non-tumor tissues." (PMID 31340767, 2019). "In this study, we found that pseudogene-derived LncRNA PTTG3P was upregulated in HCC tissues and cells, and high PTTG3P level was related to tumor size and metastasis." (PMID 31340767, 2019). "Taken together, the data indicate that knockdown of PTTG3P exerts tumor suppressive roles in inhibiting cell migration and invasion." (PMID 31340767, 2019). "Mechanically, PTTG3P is involved in tumor growth, while PTTG3P metastatic cascade promotes cells by the upregulation of PTTG1 and activation of the PI3K/AKT signalling pathway." (PMID 31341758, 2019). "(c) Representative images of PTTG3P expression from tumor xenografts established by subcutaneous transplantation with sh-con and sh-PTTG3P HepG2 cells by ISH assays." (PMID 29803224, 2018). "Consistent with the observation in the lncRNA profiling study, the level of PTTG3P was significantly higher in tumor tissues compared with that in adjacent non-tumor tissues (P < 0.05, paired Student t test)." (PMID 29803224, 2018). "We revealed that PTTG1 was frequently up-regulated and positively correlated with PTTG3P in 46 HCC tumor tissues." (PMID 29803224, 2018). "(d) Representative images of PTTG3P expression from tumor xenografts established by subcutaneous transplantation with Lv-con and Lv-PTTG3P HepG2 cells by ISH assays." (PMID 29803224, 2018).
tumor (continued). "Collectively, these data suggest PTTG3P promotes cell migration and invasion in vitro and tumor metastasis in vivo." (PMID 29803224, 2018). "We draw a schematic model of lncRNA PTTG3P functions during tumor growth and metastasis cascade in HCC." (PMID 29803224, 2018). "Artificial modulation of PTTG3P (down- and over-expression) was performed to explore the role of PTTG3P in tumor growth and metastasis in vitro and in vivo." (PMID 29803224, 2018). "In this study, we demonstrated that PTTG3P is frequently up-regulated in HCC tissues relative to corresponding adjacent non-tumor tissues from 2 cohorts by qRT-PCR and ISH assays." (PMID 29803224, 2018). "Clinically, the up‐regulation of PTTG3P was highly correlated with increased tumour burden and a higher after treatment recurrence rate, suggesting that PTTG3P facilitates tumour progression by enhancing tumour cell proliferation and invasion." (PMID 28631396, 2017). "Consistent with the ex vivo data, overexpression of PTTG3P remarkably accelerated tumour growth compared with controls in the xenograft models." (PMID 28631396, 2017). "High PTTG3P expression levels divided by the median value 14 were tightly correlated with larger tumour sizes (P = 0.043) and higher recurrence rates (P = 0.022)." (PMID 28631396, 2017). "Univariate analysis of survival revealed that the relative level of PTTG3P expression (P < 0.001), tumour grade (P < 0.001), lymphatic metastasis (P = 0.002) and TNM stage (P < 0.001) was prognostic indicators of DFS and OS." (PMID 28631396, 2017). "We previously identified systemic variations in lncRNA expression between GC and paired non‐tumour samples performed with microarray analysis 12 and noted that the pseudogene PTTG3P was up‐regulated (2.008‐fold change; P = 0.022) in GC tissues." (PMID 28631396, 2017). "Then, we utilized CCK8 and colony‐formation assays to elucidate the potential effect of PTTG3P on GC tumour cell proliferation." (PMID 28631396, 2017). "In addition, there has been a correlation between TNM stage, tumor depth, and lymph node invasion with the elevated expression of PTTG3P in ESCC." (PMID 36770654, 2023). "Huang and co-workers demonstrated that the lncRNA PTTG3P (pituitary tumor-transforming 3, pseudogene) is highly expressed in HCC, and that a higher expression of lncRNA PTTG3P is positively associated with tumor TNM stage, tumor size, and poor survival outcomes." (PMID 36010685, 2022). "Elevated upregulation of PTTG1 activated by lncRNA PTTG3P promotes tumor growth and metastasis." (PMID 35907846, 2022). "Up-regulated PTTG3P was positively linked with tumor size (P=0.02) and differentiation (P=0.01), but not with age (P=0.86), gender (P=0.74), tumor invasion depth (P=0.28), lymph node metastasis (P=0.09) or vessel invasion (P=0.06)." (PMID 34132347, 2021). "In the subcutaneous tumor model, PTTG3P overexpression facilitated tumor growth." (PMID 34660259, 2021). "In vivo, highly expressed PTTG3P efficiently increased the tumor growth." (PMID 34132347, 2021). "PTTG3P depletion and Oxaliplatin played a synergistic role in emancipating tumor growth." (PMID 34132347, 2021). "Highly expressed PTTG3P was positively associated with tumor size (p = 0.02) and differentiation (p = 0.01), but not with age (p = 0.86), sex (p = 0.74), tumor invasion depth (p = 0.28), lymph node metastasis (p = 0.09), or vessel invasion (p = 0.06)." (PMID 34660259, 2021). "However, the expression of PTTG3P is significantly upregulated in HNSCC tumor tissues compared with normal samples." (PMID 32824814, 2020). "Besides, high PTTG3P expression level promoted tumor cell proliferation, migration, and invasion and indicated bad prognosis in BC, cervical cancer, gastric cancer, and esophageal squamous cell carcinoma." (PMID 32903535, 2020). "Furthermore, PTTG3P was found to be closely related with differentiation grades (P = 0.005) and tumor size (P = 0.003)." (PMID 33298873, 2020).
tumor (continued). "Next, we examined role of FoxM1 in PTTG3P-regulated tumor cell aggressiveness." (PMID 33298873, 2020). "MiR-383 modulated the functions of PTTG3P in tumor malignant phenotypes." (PMID 31340767, 2019). "Moreover, H&E-stained liver sections revealed that control tumors showed extensive evidence of invasion into adjacent tissue, whereas PTTG3P-knockdown tumors maintained a distinct tumor–stroma boundary." (PMID 29803224, 2018). "Moreover, the level of PTTG3P was positively correlated with PTTG1 mRNA in 46 HCC tumor tissues (R = 0.543, P < 0.05)." (PMID 29803224, 2018). "Since the obligate compensatory suppression of apoptosis together with deregulated cell proliferation propelled the tumor cell and its progeny into uncontrolled expansion, we also detected the effect of PTTG3P on HCC cell apoptosis by FACS-based Annexin-V/7-AAD double staining." (PMID 29803224, 2018). "Therefore, we analysed the mRNA expression levels of PTTG3P in 63 pairs of GC tissues and adjacent non‐tumours (ANTs) and found that PTTG3P was significantly up‐regulated in 68.3% (43 of 63) of the GC tissues compared with the ANTs (P = 0.021)." (PMID 28631396, 2017). "Additionally, while PTTG2 and PTTG3P have been linked to tumor development, no prior study, to the best of our knowledge, has delved into their expression patterns and roles in LUAD." (PMID 40877987, 2025). "Additionally, we found PTTG3P could be transcriptionally activated by FoxM1, thus forming a potent feedforward circuitry to enhance PTTG3P-induced pro-tumor effect." (PMID 33298873, 2020). "PTTG3P expression level was significantly higher in stage III/IV patients than in stage I/II patients, and in patients with tumor size greater than 3 cm than in patients with tumor size less than 3 cm." (PMID 37705754, 2023). "The results showed that PTTG3P level was positively correlated with advanced tumor-node-metastasis (TNM) stage (p=0.001) and tumor size (p=0.017)." (PMID 37705754, 2023). "Pseudogene-derived lncRNAs such as PHBP1, PTTG3P, and FTH1P3 function as tumor promoters or tumor suppressors in ESCC." (PMID 34016787, 2021). "For tumor growth model, we subcutaneously transplanted PDAC cells with PTTG3P overexpression or knockdown into 5-week-old nude mice." (PMID 33298873, 2020). "In summary, our study demonstrated that pseudogene PTTG3P was upregulated in PDAC tissues and acted as an oncogene to promote tumor growth and metastasis in vitro and in vivo." (PMID 33298873, 2020). "High level of PTTG3P was found in 68.89% (62 of 90) of HCC tissues, compared with only 14.44% (13 of 90) of adjacent non-tumor tissues(P < 0.001)." (PMID 29803224, 2018). "Clinical data revealed that high levels of PTTG3P significantly correlate with the invasive and aggressive characteristics of HCC (positively correlated with tumor size and TNM stage) as well as poor survival in patients with HCC." (PMID 29803224, 2018). "To confirm the frequent up-regulation of lncRNA PTTG3P in HCCs, we further examined the expression of PTTG3P by qRT-PCR in an additional 46 pairs of HCC/non-tumor tissues (cohort 1)." (PMID 29803224, 2018). "We found that PTTG3P was frequently up-regulated in HCC and its level was positively correlated to tumor size, TNM stage and poor survival of patients with HCC." (PMID 29803224, 2018). "Furthermore, we found that the high expression of lncRNA PTTG3P in NSCLC positively correlated with an advanced TNM stage, a larger tumor size, and poor survival of NSCLC patients." (PMID 37705754, 2023). "PTTG3P in patients with lung adenocarcinoma (LUAD) is connected with shortening the metaphase to anaphase transition in mitosis, increasing cell viability after cisplatin or paclitaxel treatment, and facilitating tumor growth." (PMID 34947885, 2021).
tumor (continued). "Our findings suggest that PTTG3P, a valuable marker of HCC prognosis, promotes tumor growth and metastasis via up-regulating PTTG1 and activating PI3K/AKT signaling in HCC and might represent a potential target for gene-based therapy." (PMID 29803224, 2018). "Modulation of the tumor growth and metastasis effect through inhibiting PTTG1 up-regulation and PI3K/AKT activation mediated by PTTG3P suppression might be used as a potential target for HCC prevention and therapy." (PMID 29803224, 2018). "Further ISH studies of PTTG3P were performed in 90 paraffin-embedded HCC tumor tissues and adjacent non-tumor tissues (cohort 2)." (PMID 29803224, 2018). "High PTTG3P expression was correlated with increased tumour size and enhanced tumour invasiveness and served as an independent negative prognostic predictor." (PMID 28631396, 2017). "To determine the effect of lncRNA PTTG3P knockdown on metastasis of NSCLC cells from blood to lung, we injected A549 cells stably transfected with LV-shPTTG3P or LV-shCTR into immunodeficient mice through the tail vein, and established a tumor cell model of blood-lung metastasis." (PMID 37705754, 2023). "Intriguingly, the treatment of Hippo pathway inhibitor, XMU-MP-1 (inhibiting MST1/2), could not recover the effect of PTTG3P on proliferation, apoptosis, and tumor growth." (PMID 34132347, 2021). "The CCK8 assay showed that the absorbance of PTTG3P‐overexpressing cells was significantly higher than that of vector control‐transfected GC cells, suggesting that overexpression of PTTG3P in AGS and HGC‐27 cells leads to increased accumulation of living tumour cells (P < 0.05)." (PMID 28631396, 2017).